PPARG (peroxisome proliferator activated receptor gamma)
Diseases named in the same sentence as PPARG in open-access papers (continued):
Sharing a sentence is not in itself a finding about the gene and the disease.
Stroke (continued). "PPARγ agonists have also showed benefits in experimental models of stroke and ischemia." (PMID 25246934, 2014). "However, no study has investigated whether the pre-treatment of IR (in prediabetes or T2D) by PPARγ agonists can improve post-stroke functional recovery." (PMID 36835405, 2023). "Therefore, to a certain extent, the anti-inflammatory effect of OPC-based cell therapy for stroke might be attributed to PPARγ-mediated phospholipid metabolic reprogramming." (PMID 35547747, 2022). "Moreover, PPARγ pathway may improve stroke outcomes in the diabetic condition by decreasing neuroinflammation via NFκB inhibition and preserving the BBB integrity via tight junctions production." (PMID 33573189, 2021). "Our previous study showed that rFGF21 administration increases PPARγ DNA-binding activity three days after stroke in the perilesion cortex of T2DM mice, which might be partially responsible for the reduction of brain tissue damage and detrimental proinflammatory cytokine expressions." (PMID 32012810, 2020). "MiRNA-383 and PPARγ might serve as potential therapeutic strategies for stroke." (PMID 30622558, 2018). "These compounds exhibited strong binding affinities to key stroke-related targets such as CASP3 and PPARG, suggesting their possible pharmacological activity." (PMID 40732222, 2025). "Nevertheless, detailed molecular mechanisms for FGF21-induced PPARγ activation and downstream signaling pathways of PPARγ activation in modulating BBB integrity after T2DM stroke need to be elucidated in future investigations." (PMID 32012810, 2020). "Pioglitazone, a peroxisome proliferator-activated receptor-gamma (PPARγ) agonist used clinically as an anti-diabetic medication, is known to exert various biological functions such as reducing inflammation and oxidative injury and may use for stroke or other neurodegenerative diseases." (PMID 33105652, 2020). "The rFGF21 administration given 6 h after stroke eliminated this reduction (263.8% increase in CD36 and 199.6% increase in FABP4), which reflected the change of cerebrovascular PPARγ activity." (PMID 32012810, 2020). "Hence PPARγ agonists might be animportant class of drugs for use in stroke therapy." (PMID 21909480, 2008). "On the one hand, Sirt1 induced the deacetylation of QIK 6; on the other hand, Sirt1 activated PPARγ/PGC-1α Signal pathway, both of which could promote synthesis of triglyceride and inhibit neuronal apoptosis, thus slowing the progression of stroke." (PMID 37622049, 2023). "In a systematic review it has been proposed that PPARγ agonists probably lead to a reduction of recurrent stroke and total events of cardiovascular death, non-fatal myocardial infarction or non-fatal stroke." (PMID 36561366, 2022). "We detected a significant reduction in PPARγ DNA-binding activity in the brain tissue and mRNA levels of BBB junctional proteins and PPARγ-targeting gene CD36 and FABP4 in cerebral microvasculature at 24 h after stroke." (PMID 32012810, 2020). "Consistent with a reduced capacity to promote oligodendrogenesis, IL-4 failed to improve long-term sensorimotor or cognitive deficits after stroke in the absence of PPARγ." (PMID 31226122, 2019). "PPARγ agonists have been demonstrated to reduce recurrent stroke and total events of cardiovascular death or non-fatal stroke." (PMID 26021445, 2015). "Treatment with PPARγ agonists showed a significant improvement in functional independence measure (FIMTM), indicating that the administration of TZDs drugs improved their functional recovery by the modulation of the neuroinflammatory response following stroke." (PMID 25246934, 2014). "PPARδ and PPARγ agonists also have shown benefits in experimental models of SCI, TBI and stroke." (PMID 24215544, 2013). "In animal model, rats implanted with intracerebral EZH2-knocked-down hMSCs or hMSCs plus treatment with PPARγ agonist (rosiglitazone) showed better improvement than those without EZH2 knockdown or rosiglitazone treatment after a stroke." (PMID 23526793, 2013).
Stroke (continued). "As amorfrutin B can selectively activate PPARγ without evoking adverse effects known for TZDs, in the current study, we aimed to assess the neuroprotective properties of amorfrutin B in a cellular model of stroke and perinatal asphyxia." (PMID 34440058, 2021). "The lack of PPARγ expression in OPCs did not significantly impair oligodendrocyte replacement after stroke, as shown by comparable numbers of BrdU+APC+ cells in the ischemic brain from PPARγ-OPC KO mice and control mice at 35 d after MCAO." (PMID 31226122, 2019).
inflammatory bowel disease (77 papers, 2008 to 2026). A spectrum of small and large bowel inflammatory diseases of unknown etiology. "The GEO analysis indicate that PPARγ deficiency increased the expression of TMPRSS2 in induced inflammatory bowel disease." (PMID 34407143, 2021). "Of note, PPARγ is responsible for the selective killing of bacteria associated with inflammatory bowel disease by stimulating the expression of β-defensins and the maintenance of innate antimicrobial immunity in the colon." (PMID 32708786, 2020). "ABA can enhance PPARγ levels, and ABA-associated reductions in inflammation were observed to be PPARγ-dependent in inflammatory bowel disease and influenza." (PMID 29891920, 2018). "Studies with mice, pigs and humans have indicated that the expression of the PPARγ is implicated in the pathology of numerous diseases including inflammatory bowel disease." (PMID 30322146, 2018). "Activation of PPARγ is associated with anti-inflammation in various diseases, including inflammatory bowel disease and ischemia reperfusion-induced kidney injury." (PMID 25889216, 2015). "Peroxisome proliferator-activated receptor gamma (PPARγ), a nuclear receptor, has been implicated playing a role in the development of inflammatory bowel disease (IBD)." (PMID 22276212, 2012). "Furthermore PPARγ is thought to be one of the molecular targets underlying the beneficial anti-inflammatory effect of 5-aminosalicylic acid, a drug widely used to treat inflammatory bowel diseases (IBDs)." (PMID 19125181, 2008). "PPARγ is a potential regulator of arachidonic acid metabolism; agonists for PPARγ effectively down regulate COX-2 and 5-LOX, which is found useful in the treatment of inflammation associated disorders, for instance, inflammatory bowel disease." (PMID 36875279, 2023). "Additionally, PPARγ agonists can suppress the pro-inflammatory cytokines associated with chronic diseases such as Inflammatory Bowel Disease (IBD)." (PMID 35295337, 2022). "For example, SCFAs are the products of the gut microbiota and can activate PPARγ in the colon and regulate the process of inflammatory bowel disease (IBD)." (PMID 34740314, 2021). "Given the pivotal role in the modulation of intestinal homeostasis, PPARγ has been recognized as an important target for the treatment of inflammatory bowel disease." (PMID 33820558, 2021). "Another research study also supports the role of PPARγ in the amelioration of inflammatory bowel disease." (PMID 33498177, 2021). "PPARγ agonists mitigate inflammatory bowel disease symptoms, reduce inflammation, and are effective in multiple models of ulcerative colitis as well as in Crohn’s disease." (PMID 32708786, 2020). "A PPARγ-dependent anti-inflammatory effect of CLA was also observed in mice with inflammatory bowel disease." (PMID 30347833, 2018). "One study reported that α-eleostearic acid (cis-9,trans-11,trans-13 CLNA) ameliorated inflammatory bowel disease in mice by activating PPARγ." (PMID 30347833, 2018). "PPARγ activation inhibited xenograft growth in mice and PPARγ agonists reduced the number of aberrant cryptal foci in chemically induced inflammatory bowel disease in mice." (PMID 25866814, 2015). "PPARγ activation has been shown to ameliorate the severity of inflammatory bowel disease in rodent DSS, trinitrobenzene sulphonic acid, and ischemic colitis models." (PMID 24465207, 2014). "On the other hand, PPARγ is expressed at the intestinal level and activation of this receptor by CLA is associated with a decreased of inflammation in murine model of inflammatory bowel diseases." (PMID 24475308, 2014). "We aimed at determining the occurring PPARγ SNPs, at predicting the haplotypes, and at determining the frequency outcome in inflammatory bowel disease (IBD) patients in comparison with healthy controls." (PMID 22448164, 2012).
inflammatory bowel disease (continued). "Specifically, when activated by TZD, PPARγ inhibits the expression of several inflammatory genes in macrophages with beneficial effects, as, for instance, in inflammatory bowel diseases." (PMID 22848209, 2012). "The involvement of PPARγ in inflammatory bowel diseases was investigated in several mouse models and the general picture emerged that PPARγ activity protected from IBD." (PMID 21382489, 2011). "This study aimed to investigate whether activation of PPARγ regulates M1/M2 macrophage polarization to attenuate dextran sulfate sodium salt (DSS)‐induced inflammatory bowel disease (IBD) via the STAT‐1/STAT‐6 pathway in vivo and in vitro." (PMID 39737788, 2025). "The aryl hydrocarbon receptor (AhR) and the peroxisome proliferator-activated receptor γ (PPARγ) are ligand-activated transcription factors that have in recent years been investigated for their anti-inflammatory properties for treatment of inflammatory bowel diseases (IBDs)." (PMID 39684781, 2024). "A Boolean network explorer (BoNE) computational algorithm was used to identify a dual agonist of the nuclear receptors PPARα and PPARγ that may be therapeutic in treating inflammatory bowel disease." (PMID 35288651, 2022). "For example, glucocorticoids have inhibited inflammatory bowel disease through the PPARγ pathway." (PMID 35517804, 2022). "Thus, PPARγ can become a potential therapeutic target for inflammatory bowel diseases, for instance, because PPARγ is highly expressed in the gut." (PMID 33467433, 2021). "Moreover, PPARγ is also an important target of 5-aminosalicylic acid, one of the oldest anti-inflammatory agents used for the treatment of inflammatory bowel disease." (PMID 33820558, 2021). "Furthermore, colonic PPARγ expression was upregulated in mice chemically induced with inflammatory bowel disease following dietary intervention with 5% DF from resistant starch and soluble maize fibre." (PMID 30322146, 2018). "Moreover, lipocalin 2 modulated by PPARG could be a potential pathway involved in concurrent inflammation and ankylosis in inflammatory bowel diseases and ankylosing spondylitis." (PMID 37254181, 2023). "PPARγ agonists mitigate inflammatory bowel disease (IBD) symptoms, reduce inflammation, and are effective in multiple models of ulcerative colitis as well as in Crohn’s disease." (PMID 30060580, 2018). "More importantly, activation of PPARγ modulates mucosal immune responses and is involved in the prevention of inflammatory bowel disease (IBD) in mice, pigs, and humans." (PMID 23071818, 2012). "CB2R agonism combined with PPARγ or 5-HT4R agonist activity may be used for treating Inflammatory Bowel Disease (IBD)." (PMID 35295337, 2022). "Indeed, stigmasterol has been shown to up-regulate the intestinal mucosal immune response involved in inflammatory bowel disease (IBD) by activating the butyrate-PPARγ axis in colitis." (PMID 36290632, 2022). "Using qPCR and IHC, we compared β-catenin, PPARγ, COX-2, and IL-17A in the colonic mucosa of patients with sporadic CRC, inflammatory bowel disease (IBD), and irritable bowel syndrome (IBS), against a normal control population." (PMID 30186819, 2018). "Inflammatory bowel diseases (IBD) (Crohn's disease and ulcerative colitis) are inflammatory conditions in which the role of PPARγ was investigated." (PMID 21382489, 2011). "For example, the combination of anti-inflammatory drugs for experimental inflammatory bowel disease (IBD) and PPARG may become a new method for the treatment of IBD." (PMID 37334066, 2023).
inflammatory bowel disease (continued). "Octanoic acid‐rich enteral nutrition could regulate the M1/M2 polarization of intestinal macrophages and simultaneously repair the intestinal mucosal barrier by activating the PPARγ/STAT‐1/STAT‐6 pathway, thereby significantly alleviating inflammatory bowel disease‐induced intestinal injury." (PMID 41256230, 2025). "While there are not many studies that focus on the effect of Se and PPARγ on inflammatory bowel diseases and the mechanism through which Se acts, one can make conjectures based on the available data using murine models of IBD." (PMID 29494512, 2018). "Anthocyanins increased the expression of peroxisome proliferator-activated receptor γ (PPARγ) and inhibited the activation of the downstream NF-κB/MAPK signaling pathway, thereby alleviating colonic inflammation on dextran sulfate sodium-induced inflammatory bowel disease (IBD) in mice." (PMID 38053560, 2023).
melanoma (74 papers, 2008 to 2025). A malignant, usually aggressive tumor composed of atypical, neoplastic melanocytes. "Strong PPARγ immunoreactivity in melanoma cells was associated with improved PFS in retrospective analysis." (PMID 38273846, 2023). "Interactions with tumor-associated fibroblasts and endothelial cells suggest that PPARγ is involved in melanoma proliferation and angiogenesis, leading to melanoma progression and metastasis." (PMID 36834531, 2023). "The PPARγ expression in the melanoma cell lines (A375, M24met, 1205Lu, MelJuso), in HUVECs, normal fibroblasts (NHDFs) and primary melanoma associated fibroblasts (MP9, MP10, MP11, MCM16 fibroblasts) was confirmed via Western blotting." (PMID 23049949, 2012). "This study was designed to investigate consequences of PPARγ activation for melanoma and melanoma-associated stroma cells." (PMID 23049949, 2012). "We have demonstrated that S100A2 levels are low in the A375(DRO) melanoma cell line, and these levels are increased by treatment with PPARγ and RXR agonists, which is associated with a significant reduction in growth and increase in apoptosis." (PMID 19859558, 2010). "Accordingly, tumor-associated inflammatory and angiogenic processes mediated by COX2 overexpression or PPARG deficiency were suggested to play a pivotal role in the biology of melanoma progression." (PMID 19639032, 2009). "Finally, we show that B16F10 melanoma tumor growth is enhanced in syngeneic C57.Pparg-/-epi mice, indicating that loss of epidermal PPARγ acts through indirect mechanisms to regulate tumor growth." (PMID 29228682, 2017). "In addition to direct effects on cancer cells, PPARγ agonists were tested on the influence on cells of the tumor microenvironment such as endothelial cells and melanoma associated fibroblasts." (PMID 23049949, 2012). "In a search for genetic factors that may increase melanoma risk, correlation between PPARγ variants and melanoma development in a Caucasian population indicated that PPARγ polymorphisms are an unlikely risk factor for melanoma development in this population." (PMID 19125181, 2008). "PPARγ activation has been reported to be a link to melanocyte differentiation pathways, as suggested by the ability of PPARγ ligands to regulate Microphthalmia-associated transcription factor gene and Wnt/β-catenin levels, promoting differentiation and growth arrest of melanoma cells." (PMID 25101957, 2014). "A study showed that CPT1A was upregulated in melanoma cells through the Wnt5a/β-catenin/PPARγ pathway, which in turn led to enhanced FAO in dendritic cells." (PMID 40514365, 2025). "A large number of studies suggest that PPARγ also acts as a skin tumor suppressor in both melanoma and non-melanoma skin cancers, but its role in tumorigenesis remains controversial." (PMID 38927131, 2024). "COX2/PPARγ tissue immunoreactivity significantly increases stage-dependently from primary melanoma to metastases." (PMID 38273846, 2023). "Activation of PPARγ led to reduced expression of thioredoxin-interacting protein (TXNIP) in human melanoma A375 cells." (PMID 36834531, 2023). "The data obtained from the Human Protein Atlas confirmed that PPARγ is weakly expressed in melanoma tissue." (PMID 36834531, 2023). "Previous studies revealed that activation of PPARγ by cloxiquine resulted in decreased metastasis of melanoma cells in a mice model." (PMID 36834531, 2023). "The biological role in cancer cell proliferation of PPARs has been extensively studied, and PPARγ activity in melanoma is especially well-documented." (PMID 36834531, 2023). "Consistently, in peripheral T cells, SPHK1-generated S1P binds PPARγ for its transcriptional activation, and the inhibition of SPHK1/S1P/PPARγ signaling ameliorates antitumor immunity against mouse melanoma." (PMID 35565311, 2022). "In melanoma cells, stimulation of PPARγ by its ligand pioglitazone influences the process triggered by Toll-like receptors (TLRs) with a reduction of the inflammatory state." (PMID 35453308, 2022).